REN (renin)
Diseases named in the same sentence as REN in open-access papers (continued):
Sharing a sentence is not in itself a finding about the gene and the disease.
anemia (continued). "LVSD in patients with PD can partially be attributed to factors such as a chronic inflammatory state, uremia toxin, anemia, fluid retention, hyperparathyroidism, renin-angiotensin-aldosterone activation, an increased serum calcium-phosphate product, and glucose load." (PMID 36530903, 2022). "The low Hb levels in children with APN may be due to activation of the renin–angiotensin–aldosterone system, leading to enhanced tubular reabsorption of water and consequent dilutional anemia." (PMID 34689744, 2021). "The development of left ventricular hypertrophy (LVH) involves classic factors suchas anemia, changes in renin-angiotensin-aldosterone system (RAAS), and hypertensionin addition to the independent mechanisms from the mTOR, phosphorus, and parathyroidhormone (PTH)." (PMID 29738042, 2018). "To date, several other possible explanations for anemia have been proposed, such as direct apoptotic effects of ACEi on erythroid precursor cells, drug toxicity, and accumulation of substrates of renin or ACE." (PMID 26107632, 2015). "Anemia increases peripheral and myocardial tissue hypoxia, enhances the levels of pro-inflammatory cytokines, leads to LV dilatation and eccentric remodeling and activates the sympathetic nervous system and renin-angiotensin-aldosterone axis." (PMID 24086579, 2013). "Finally, the results indicate that the iron deficiency is driven by hepcidin accumulation in blood due to decreased GFR.There were several reports in which anemia has been demonstrated in RAS-deficient mice including ACE knockout, Agt-KO, renin knockout, and double AT1aR/AT1bR receptor knockout." (PMID 39869503, 2025). "Therefore, inhibition of the renin-angiotensin system with the use of these medication classes could indirectly lead to anaemia through upregulation of stimulators and downregulation of inhibitors of hematopoiesis." (PMID 38463117, 2024). "Although there is limited evidence regarding the relationship between ARNi use and haemoglobin concentration, the literature suggests that similar to other medications inhibiting the renin-angiotensin system, ARNi could join other existing factors in HF patients for the development of anaemia." (PMID 38463117, 2024). "Concomitant activation of the renin-angiotensin system (RAS) increased cardiac afterload, while Anemia and malnutrition further diminished myocardial energy supply." (PMID 41561737, 2025). "Interstitial renin-expressing cells (bottom, left) can undergo an endocrine shift in response to an acute stabilization of HIF-2α due to anemia or the administration of PHD inhibitors." (PMID 35511367, 2022). "It has been observed in mice that during anemia or after pharmacological inhibition of PHDs a subpopulation of interstitial cells coexpresses EPO and renin suggesting an endocrine plasticity of these cells." (PMID 35511367, 2022). "It is known that the activation of renin-angiotensin system enhances the erythropoietin productions, while its inhibition due to ACE inhibitors may exacerbate anaemia." (PMID 31521117, 2019). "Debate is still on-going regarding the potential effects of renin-angiotensin system inhibitors, such as angiotensin-converting enzyme (ACE) inhibitors or angiotensin II-receptor antagonists (ARBs), on the development of anaemia in patients with renal disease." (PMID 31521117, 2019). "Fifth, treatments known to influence diastolic dysfunction, including blood pressure control, use of diuretics, blockade of the renin-angiotensin system, correction of anemia, and coronary revascularization were not considered in our analysis." (PMID 25739020, 2015). "In our study, there was no obvious effect of renin-angiotensin system inhibitors on anaemia." (PMID 30290796, 2018).
congestive heart failure (60 papers, 2009 to 2025). Failure of the heart to pump a sufficient amount of blood to meet the needs of the body tissues, resulting in tissue congestion and edema. "Considering that congestive heart failure is relatively common after cardiac surgery arouses the suspicion of its possible role to cause electrolyte imbalances through activation of the renin-angiotensin-aldosterone system." (PMID 31086514, 2019). "The underlying mechanism of congestive heart failure is afterload mismatch due to stenotic proximal aorta and activation of renin-angiotensin-aldosterone system due to renal ischemia." (PMID 28203578, 2017). "Interestingly, the disturbance of serum chloride level (hypochloremia) and different kinds of chloride channels have been observed to have adverse effect on acute and chronic heart failure, by causing dysregulation of renin secretion and fluid retention." (PMID 35971449, 2022). "In fact, it is known that, in patients with chronic heart failure, the renin-angiotensin-aldosterone system is activated, and it has even been shown that the activity of increased plasma renin levels directly contributes to mortality." (PMID 39906471, 2025). "Chronic heart failure also triggers sympathetic nerve activation and the renin–angiotensin–aldosterone system, promoting a hypercoagulable state." (PMID 40943803, 2025). "In patients with chronic heart failure, neurohormonal activation—particularly of the sympathetic nervous system and the renin–angiotensin–aldosterone system (RAAS)—plays a pivotal role in disease progression." (PMID 40943803, 2025). "Body weight, serum biochemical variables, and renin‐angiotensin‐aldosterone system components were measured during hospitalization for congestive heart failure." (PMID 39482042, 2024). "Although the exact pathophysiology of the heart diseases underlying congestive heart failure (CHF) differ between man and his best friend, overactivation of the renin–angiotensin–aldosterone system (RAAS) plays a key role in the pathogenesis and development of CHF in both humans and dogs." (PMID 36843132, 2023). "The renin–angiotensin–aldosterone-systems (RAAS) play a central role in the pathophysiology of congestive heart failure (CHF), justifying the use of angiotensin converting enzyme inhibitors (ACEi) in dogs and humans with cardiac diseases." (PMID 36843132, 2023). "A previous study demonstrated elevations in renin, angiotensin II, and atrial natriuretic peptide in dogs with advanced heartworm disease characterized by congestive heart failure or caval syndrome." (PMID 37106412, 2023). "The cornerstone of the treatment of chronic heart failure is to inhibit the renin-angiotensin-aldosterone system (RAAS)." (PMID 35222898, 2022). "Congestive heart failure can lead to fibrosis through increased LA stretch and neurohormonal activation through the renin-angiotensin-aldosterone axis." (PMID 36386377, 2022). "An important feature of the pathogenesis of hypertension and chronic heart failure is the activation of the neurohormonal system, including the renin-angiotensin-aldosterone system (RAAS) and the sympathetic nervous system (SNS)." (PMID 35222898, 2022). "Randomized controlled trials in patients with chronic heart failure have demonstrated benefit of several interventions such as beta-adrenergic receptor blockade or inhibitors of the renin–angiotensin–aldosterone system." (PMID 33413345, 2021). "Before admission, patients with worsening chronic heart failure and reduced ejection fraction were treated with renin–angiotensin system blockers (60.4%), beta‐blockers (42.5%), or spironolactone (34.4%)." (PMID 33179453, 2021). "A previous report indicated that gene expression of (P)RR, renin, and angiotensinogen is increased in the heart with chronic heart failure in rats." (PMID 34367278, 2021).
congestive heart failure (continued). "Patients with remote MI and congestive heart failure present complex neuro-hormonal responses including enhanced sympathetic drive and activation of the renin–angiotensin–aldosterone system." (PMID 32019245, 2020). "The renal function of patients with congestive heart failure is affected due to many factors such as activation of the sympathetic nervous system, activation of the renin-angiotensin system, and an increase in anti-diuretic hormone (ADH) levels." (PMID 30216349, 2018). "Accumulated evidence shows that the ACE-AngII-AT1 axis of the renin-angiotensin system (RAS) is markedly activated in chronic heart failure (CHF)." (PMID 24859374, 2014). "In addition, excessive hypotension is a possibility in patients with intense renin-dependent vasoconstriction, hyponatremia, and congestive heart failure (CHF)." (PMID 34198801, 2021). "In addition to its link with HTN and BP response, sphingosine-1-phosphate has also been shown to alleviate congestive heart failure induced by increased cardiac renin release." (PMID 34564461, 2021). "Patients with congestive heart failure (CHF) have chronic sympathetic nervous system and renin–angiotensin–aldosterone system (RAAS) stimulation, which leads to vasoconstriction and sodium and water retention." (PMID 40218406, 2025). "Chronic activation of the renin‐angiotensin‐aldosterone system (RAAS) plays an important role in the pathogenesis of congestive heart failure (CHF) both in human and veterinary patients." (PMID 34994485, 2022). "One could also argue that the TAC model represents primary renal malfunction (decreased renal perfusion due to reduced SV, leading to renin secretion and angiotensin formation), followed by gradual development of angiotensin-II dependent chronic heart failure, therefore modelling CRS." (PMID 34211391, 2021). "Renin‐angiotensin‐system blockers (RASB) improve clinical outcomes in patients with chronic heart failure with reduced fraction; however, there remains ambiguity whether RASB therapy should be continued during the treatment of acute decompensated heart failure (ADHF)." (PMID 31498919, 2019). "Thus, the pathophysiology of depressed LVEF in this setting may be very different from chronic heart failure involving the sympathetic nervous system and renin-angiotensin-aldosterone system." (PMID 25530906, 2014). "In chronic heart failure patients, renal salt and water homeostasis alterations are primarily driven by activation of the renin-angiotensin-aldosterone system and the non-osmotic release of arginine vasopressin." (PMID 40104143, 2025). "Since the establishment of beta-blockers and renin-angiotensin-aldosterone system inhibitors as chronic heart failure treatment agents that can improve long-term prognosis, no novel drugs as a breakthrough for chronic heart failure have emerged." (PMID 35077456, 2022). "Patients who develop left ventricular dysfunctions are currently treated with the standard medical therapy for chronic heart failure, typically β-blockers and inhibitors of the renin-angiotensin system, which are usually not sufficient to prevent heart transplantation." (PMID 31118417, 2019). "NEPi enhances the activity of natriuretic peptide systems leading to natriuresis, diuresis and inhibition of the renin–angiotensin system (RAS), which could act as a potentially beneficial counter-regulatory system in states of RAS activation such as chronic heart failure (HF) and CKD." (PMID 25140014, 2015). "Together, NPs balance the effects of the renin–angiotensin–aldosterone system (RAAS), which is hyperactive during heart disease, promoting cardiac remodeling, and inducing congestive heart failure (CHF)." (PMID 29062197, 2017).
left ventricular hypertrophy (56 papers, 2009 to 2026). Enlargement of the LEFT VENTRICLE of the heart. "FGF23, a hormone for regulation of phosphate hemostasis and the renin–angiotensin–aldosterone system, is an indicator of both renal and myocardial dysfunction and is associated with left ventricular hypertrophy and clinical outcomes." (PMID 33439866, 2021). "This is most likely due to the fact that significant RAS causes activation of the renin-angiotensin-aldosterone system with aldosterone as the strongest promoter of left ventricular hypertrophy." (PMID 28807045, 2017). "The renin-angiotensin-aldosterone system is especially susceptible to vitamin D since it negatively regulates renin and is correlated with a decrease in blood pressure and left ventricular hypertrophy." (PMID 36110560, 2022). "The renin (REN) gene encodes protease renin which plays a central role in regulating blood pressure, and activation of the renin-angiotensin system is linked to the development of left ventricular hypertrophy." (PMID 32903789, 2020). "For example, FGF-23 may activate the renin-angiotensin-aldosterone system (RAAS), which is linked to a multitude of pathologic processes, including left ventricular hypertrophy, through suppression of 1,25(OH)2D, which would increase renin expression." (PMID 30120363, 2018). "Prior research has established that the activation of the renin–angiotensin–aldosterone system (RAAS) is pivotal in the progression of left ventricular hypertrophy (LVH), ultimately leading to the production of Ang II." (PMID 40753540, 2025). "Vitamin D is known to influence heart function by regulating the expression of the renin gene, angiotensin II, reducing left ventricular hypertrophy, and the proliferation of vascular smooth muscle cells." (PMID 41536823, 2025). "During the experimental study, dietary phosphate consumption increased 1,25(OH)2D levels, plasma renin concentrations, blood pressure, and left ventricular hypertrophy." (PMID 37968749, 2023). "The mechanistic actions of PTH to hypertension include the increase in renin secretion as well as its direct effects on arteries and myocytes to promote arterial stiffness and left ventricular hypertrophy." (PMID 36364791, 2022). "These rats also developed an increase in renin activity, hypocalcemia, and left ventricular hypertrophy." (PMID 35622729, 2022). "Increased afterload due to higher systemic arterial pressure (presence of vasoactive substances and consequence of inappropriate renin–angiotensin stimulation due to transfer from donor) leads to left ventricular hypertrophy." (PMID 36421215, 2022). "Estimated direct and mediated effects of FGF23 on left ventricular hypertrophy (LVH) for each of the renin-angiotensin-aldosterone system (RAAS) parameters of interest." (PMID 35559350, 2022). "A possible causal relationship was also described between FGF-23 and adverse cardiovascular remodeling, involving left ventricular hypertrophy, renin-angiotensin system upregulation and the promotion of vascular calcification." (PMID 35211520, 2022). "High phosphate diet increased blood pressure, plasma renin activity, angiotensin II, left ventricular hypertrophy, and PTH in rats.The addition of lanthanum carbonate, a phosphate binder reversed these changes." (PMID 36364791, 2022). "In that experimental study, dietary phosphate resulted in elevated 1,25(OH)2D concentrations, elevated plasma renin concentrations, elevated blood pressure, and left ventricular hypertrophy." (PMID 30057603, 2018). "Inhibitors of the renin-angiotensin system, such as angiotensin-converting enzyme inhibitors and ARBs, prevented the generation of primary atrial fibrillation in patients with left ventricular hypertrophy and/or HF." (PMID 32372277, 2020).
left ventricular hypertrophy (continued). "Adiposity increases hemodynamic stress which activates the renin-antiotensin-aldosterone system leading to elevated aldosterone levels, which again increases blood volume and cardiac output and thereby contributes to left ventricular hypertrophy." (PMID 29417316, 2018). "Renin-angiotensin system and mechanical stretch are activated after abdominal aortic constriction, a well known model of pressure overload induced left ventricular hypertrophy." (PMID 29267303, 2017). "Studies have demonstrated that all components of RAS (e.g., renin, angiotensinogen, ACE and AngII receptors) are identified in the heart at both the mRNA and the protein levels and that RAS is activated in experimental left ventricular hypertrophy induced by hemodynamic overload." (PMID 25739102, 2015).
atrial fibrillation (55 papers, 2008 to 2026). A disorder characterized by an electrocardiographic finding of a supraventricular arrhythmia characterized by the replacement of consistent P waves by rapid oscillations or fibrillatory waves that vary in size, shape and timing and are accompanied by an irregular ventricular response. "While age and sex are determinants of TTS, the neutrophile/lymphocyte ratio, renin–angiotensin system, and atrial fibrillation are shown to be associated with prognosis of TTS." (PMID 37371575, 2023). "This systematic review and meta-analysis evaluates the association of preoperative renin-angiotensin system inhibitors with prevention of postoperative atrial fibrillation and adverse events among patients undergoing cardiac surgery." (PMID 31150082, 2019). "The renin-angiotensin-aldosterone system is associated with the pathological mechanism of atrial fibrillation." (PMID 23599726, 2013). "In a similar manner, the renin-angiotensin-aldosterone system has a marked correlation with atrial remodeling which is closely associated with the development and maintenance of atrial fibrillation." (PMID 23599726, 2013). "A relation between vitamin D and RAAS has also been established as studies have shown that vitamin D deficiency increases renin levels and thus might also increase the risk of hypertension—one of the major risk factors of atrial fibrillation." (PMID 39941553, 2025). "This may be due to the activation of the renin-angiotensin-aldosterone system by persistent hypochloremia, causing atrial remodeling, which may have influenced the occurrence of atrial fibrillation." (PMID 36835793, 2023). "However, results of clinical trials evaluating the effect of renin–angiotensin–aldosterone blockers on adverse clinical outcomes in high cardiovascular disease risk subjects with atrial fibrillation remain inconclusive." (PMID 27368043, 2016). "A previous study using an atrial fibrillation pig model showed that atrial myocytes express all components of the renin-angiotensin system and undergo structural changes in response to rapid atrial pacing." (PMID 30581499, 2018). "A pooled study of 6 randomized controlled trials assessing the efficacy of renin–angiotensin–aldosterone blockers on subjects with atrial fibrillation was performed." (PMID 27368043, 2016). "Application of renin–angiotensin–aldosterone system blockers for prevention of recurrence of atrial fibrillation and adverse clinical outcomes in subjects with atrial fibrillation is a theoretically appealing concept." (PMID 27368043, 2016). "Some studies suggest that polymorphisms in the renin-angiotensin- aldosterone system alter activation of the renin-angiotensin- aldosterone system and increase the likelihood of atrial fibrillation." (PMID 25723521, 2015). "The activated renin-angiotensin-aldosterone system (RAS) has been reported to play an important role in the pathogenesis of atrial fibrillation." (PMID 25723521, 2015). "Recent studies have suggested that tolvaptan may reduce the occurrence of atrial fibrillation after cardiac surgery by inhibiting the activation of the renin–angiotensin–aldosterone axis and sympathetic nervous system." (PMID 36803437, 2023). "The activation of the renin-angiotensin-aldosterone system leads to an increase in Ang II expression, promotes atrial fibrosis remodeling and electrical remodeling, and increases the risks of atrial fibrillation incidence." (PMID 34872449, 2021). "There is some evidence that inhibitors of the renin-angiotensin system may provide more protection against LA diseases, such as atrial fibrillation." (PMID 25674752, 2015). "As Cx (NEPI) also inhibits the degradation of active-renin or Ang II, it may show an inverse effect on preventing the construction of the atrial fibrillation substrate." (PMID 18379655, 2008).